EGFR (epidermal growth factor receptor)
Diseases named in the same sentence as EGFR in open-access papers (continued):
Sharing a sentence is not in itself a finding about the gene and the disease.
cancer (continued). "Additionally, elevated EGFR signalling caused by excess ADAM17 activity is associated with cancer progression." (PMID 27731361, 2016). "It is worth noting that mutations in any of these three genes may affect their predictive utility in this context, however this rarely occurs in HER2+ cancers (less than 10% harbor mutations in EGFR, ERBB3, or CDKN1B)." (PMID 27035903, 2016). "Therefore, it is easy to miss mutations by DNA sequencing in cancer tissue specimens with low rate of EGFR-mutated cells, which are detectable by IHC." (PMID 27418143, 2016). "Hence, in CD24-positive cancer cells, EGFR keeps its association with lipid rafts on the membrane that is necessary for its signaling transduction and reducing its internalization and degradation." (PMID 26830684, 2016). "Overexpression of EGFR signaling has also been linked to the majority of cancers." (PMID 26881213, 2016). "Additionally, higher expression levels of EGFR have been associated with more aggressive cancer behavior." (PMID 27245053, 2016). "When the EGFR on the surface of cells is mutated and becomes active, it can lead to cancer growth." (PMID 27649127, 2016). "In line with driver functions, EGFR‐associated poor prognostic signatures are highly expressed in basal‐like tumors, and blocking EGFR using either kinase inhibitors or monoclonal antibodies effectively retards growth of basal‐like cancer cells." (PMID 27485121, 2016). "EGFR mutations are related to the pathogenesis of many types of cancers including NSCLC." (PMID 27217997, 2016). "Several lines of evidence suggest that cellular and humoral immune responses to EGFR might be useful as a marker and/or target for cancer therapy against EGFR-associated tumors." (PMID 27833557, 2016). "Approximately 20% lung cancer patients occupy EGFR mutations that promote cancer cell growth." (PMID 26575584, 2016). "Furthermore, there was an inverse association of BIM deletion polymorphism with DCR in EGFR-mutated NSCLC cancer patients (Ph = 0.941, OR = 0.370, 95%CI = 0.202–0.678)." (PMID 26076815, 2015). "Aberrant epidermal growth factor receptor (EGFR) signaling may cause dysregulation of microRNA (miRNA) and gene regulatory networks, which leads to cancer initiation and progression." (PMID 25756961, 2015). "Considering these reports, LL-37 can be associated with dual aspects of cancer progression via various receptors, such as epidermal growth factor receptor (EGFR), FRP2, ERBb2, P2X7, and GAPDH, or suppression via interaction with peptide-based factors and cancer membrane components." (PMID 26175965, 2015). "Furthermore, data overwhelmingly suggest that this pathway is aberrantly activated in human cancer, mostly by mutations of EGFR or RAS and RAF downstream components." (PMID 26084290, 2015). "Thus, the mutated EGFR that lead to constitutive activation of EGFR signaling is oncogenic and is therefore attractive as a cancer therapeutic molecular target." (PMID 25714021, 2015). "Since the over-expression of EGFR causes human cancers, EGFR is an attractive drug target." (PMID 25885222, 2015). "However, EGFR mutations were detected with similar frequency (p = 0.495) in samples containing ≥20 and <20 % of cancer cells." (PMID 25086987, 2015). "Notably, we assessed one such case (Patient #19), and this cancer had loss of RB and EGFR expression, similar to the cases of EGFR mutant SCLC observed in the setting of acquired resistance to EGFR TKI." (PMID 25758528, 2015). "Further understanding of the molecular regulation of stress-internalized EGFR sorting and its influence on receptor TK activation and downstream signalling will be critical for interpreting its manipulation to increase cancer cell susceptibility to chemotherapy." (PMID 26066081, 2015). "EGFR expression is linked to poor prognosis in numerous cancers." (PMID 26503469, 2015).
cancer (continued). "To assess the role of the EGFR-L858R mutation in cancer cell invasion ability and involvement in the formation of MPE, we used two H1299-derived NSCLC cell lines—H1299-EGFR-WT, overexpressing wild-type EGFR, and H1299-EGFR-L858R, overexpressing EGFR-L858R—as a model system." (PMID 26338423, 2015). "Indeed, somatically acquired mutations in EGFR, which evade ubiquitin-mediated sorting to degradation, are widespread in cancer." (PMID 25872741, 2015). "As far as EGFR is concerned, many previous studies have suggested that expression of high levels of EGFR is associated with progress, metastasis and poor prognosis of cancer patients, but the prediction power of this single receptor for patients’ outcome is controversial." (PMID 26161893, 2015). "EGFR gene is either mutated or shows altered expression in a variety of human cancers." (PMID 26580964, 2015). "However, ligand-independent activation of EGFR exists in certain cancer cells, and the underlying mechanism remains to be defined." (PMID 26378037, 2015). "Similarly, activating mutations in KRAS and BRAF, which are essential downstream effectors of the EGFR, are among the most common mutations found in a very wide range of human cancers." (PMID 26683696, 2015). "EGFR activation is a major cause of metastasis in many cancers." (PMID 25595899, 2015). "Vorinostat-induced acetylation-enhanced tyrosine kinase phosphorylation of EGFR may overcome or delay the development of acquired resistance to gefitinib caused by the low abundance of EGFR-mutant cancer cells." (PMID 25552401, 2015). "In addition to EGFR mutations, we also evaluated another 50 oncogenes thought to have an important role in cancer pathogenesis." (PMID 26572169, 2015). "Here, we hypothesized that EGFR T790M-harboring cancer cells could be targeted by activated immune cells, and attempted to assess the immunogenicity of the EGFR T790M mutation-derived antigen in vitro." (PMID 25532027, 2015). "Therefore the aberrant activation of EGFR has been associated with various cancers through several mechanisms including receptor overexpression, mutation, receptor ligand overexpression, and ligand-independent activation." (PMID 26503469, 2015). "All of the resistant SCLC cancers harboured the original activating EGFR mutation." (PMID 25758528, 2015). "It means that afatinib is more effective in EGFR-mutated cancer cells." (PMID 26317651, 2015). "The increased activity of MMP-2 suggests that PAR-2 may be implicated in cancer invasion by the MMP/EGFR/MAPK/ERK1/2 pathway." (PMID 26573921, 2015). "Aberrant activation of EGFR by copy number amplification, protein overexpression or point mutation is closely related with unregulated proliferation, malignant transformation, invasion, metastasis and resistance to apoptosis of cancer cells." (PMID 25955731, 2015). "Most importantly, however, a pathologic decrease in MIG-6 expression has been detected in several human carcinomas, which could be linked to aberrant EGFR signaling and a more aggressive disease course." (PMID 26065894, 2015). "On the other hand, isoform-specific dependencies revealed cancer associated isoforms of EGFR." (PMID 25034693, 2014). "Together, enhanced expression of FGFR1 and FGF2 thus plays as an escape mechanism for cell survival of afatinib-resistant cancer cells, that may compensate the loss of EGFR-driven signaling pathway." (PMID 25115383, 2014). "Consequently, mutations of the EGFR have been identified in several types of cancer and it is the target of an expanding class of anticancer therapies." (PMID 24658383, 2014). "EGFR is implicated in a variety of cancers and frequently mutated in AC." (PMID 24722523, 2014). "The epidermal growth factor receptor (EGFR), a member of the Her (ErbB) family of cell-surface receptors, is critical to a variety of cellular processes and is implicated in the development of several forms of cancer and other diseases." (PMID 25058506, 2014).
cancer (continued). "The molecular mechanism regulating the EGFR endocytic pathway is very complex and tightly controlled by a variety of proteins However, dysfunction of these mediators is currently implicated in human cancers." (PMID 24658031, 2014). "A very common mutation in the EGFR signaling pathway in cancer is the Kras mutation." (PMID 25502773, 2014). "Moreover, it was found afterwards that the avian erythroblastic leukemia viral (ErbB) oncogene encodes a truncated EGFR form, which suggests that EGFR plays a role in tumorigenesis and can be used as a molecular target for cancer therapy." (PMID 24709958, 2014). "The crystal structures of EGFR-L858R and EGFR-T790M have shown that these cancer-causing modifications could stabilize the active kinase form." (PMID 24817905, 2014). "In addition, at the same time, the prevention of skin disorder associated with anti-epidermal growth factor receptor (EGFR) antibody therapy is important to continue the cancer therapy." (PMID 24517087, 2014). "Our results revealed that cancer cells harboring EGFR-activating mutations could turn off EGFR signaling and lose EGFR signal addiction." (PMID 25343452, 2014). "In terms of wound regeneration, it is important to note that the administration of EGFR inhibitors (which block EGF as well as TGF-α signaling) for cancer treatment causes adverse cutaneous side effects, and in some cases interferes with wound healing in humans." (PMID 25360592, 2014). "Therefore, we conducted a meta-analysis on the published studies to evaluate the effect of EGFR R521K polymorphism with the risk of cancer." (PMID 25401099, 2014). "Mutations affecting the epidermal growth factor receptor (EGFR) expression or activity could result in cancer." (PMID 24352766, 2014). "The cancer cells harbored a positive EGFR mutation and secreted amylase." (PMID 29147375, 2014). "Mutations that cause constitutive activation of EGFR are commonly observed in human cancers." (PMID 25144461, 2014). "CRC is the third leading cause of cancer related deaths worldwide; many preclinical and clinical evidences suggested that EGFR aberrant signaling is implicated in progression of CRC, through activation of downstream pathways of ERK1/2 and AKT leading to cell proliferation and survival." (PMID 28548075, 2014). "Therefore the net effect of p27Kip1 loss and EGFR overexpression on cancer cell metastasis needs to be further investigated." (PMID 25121353, 2014). "Finally, we use our combined classifier to produce a numerical ranking of cancer-associated mutations in EGFR and test the impact of predicted mutations on EGFR kinase activity using cell-based assays." (PMID 24743239, 2014). "Aberrant enhancement of EGFR signaling, which can be caused by overexpression, increase in gene copy number or ligand-independent mutated receptors, leads to cancer-driving processes such as augmented proliferation, angiogenesis, migration/invasion, and impaired apoptosis." (PMID 25601901, 2014). "It is also used as the first treatment in patients whose cancers have a mutation in the EGFR gene." (PMID 24760004, 2014). "Therefore, changes in EGFR localization and signaling are implicated in various human diseases, including different types of cancer." (PMID 24785082, 2014). "In the EGFR gene, for example, we detected L858R (in II-18 and H1975) and E746_A750del mutations (in PC-9 and H1650), which are known to be sensitive to the anti-cancer drugs, gefitinib and erlotinib." (PMID 25378332, 2014). "Similarly, mutations in cancer genes (such as EGFR) that are selectively targeted by small-molecule inhibitors can either enhance or disrupt drug binding and thereby modulate cancer drug response." (PMID 25036042, 2014). "However, its aberrant activity in the pathogenesis of human cancers underlies our need to understand the complex regulation of EGFR activity and downstream signaling events." (PMID 24295852, 2014).
cancer (continued). "In addition, the adenocarcinoma EGFR gene mutation rate (77/139) was significantly higher than that in squamous cell (8/36) and large cell (0/1) carcinoma." (PMID 25013503, 2014). "Enhanced EGFR signaling within the intestinal stroma may play an important role in the development and progression of inflammation-associated cancer." (PMID 23688423, 2013). "In cancer, however, EGFR is often perpetually stimulated because of the sustained production of EGFR ligands in the tumor microenvironment or as a result of a mutation in EGFR itself that locks the receptor in a state of continual activation." (PMID 23986907, 2013). "Thus, IL-6 production from EGFR-TKI-treated cancer cells increases the risk of chemoresistance and acute interstitial pneumonia." (PMID 23592411, 2013). "The overexpression and mutations of EGFR are identified in the majority of cancer types." (PMID 24273605, 2013). "However, as patients are told that the development and intensity of an exanthema are rather associated with a better prognosis, the withdrawing of EGFR inhibitors from cancer therapy can be perturbing for the respective patients." (PMID 23918349, 2013). "The identification of germline biomarkers that can predict whether a cancer is predisposed to activating mutations in the EGFR pathway would therefore be an extremely useful therapeutic tool." (PMID 24152305, 2013). "In contrast, it is less clear whether germline genetic variants in the EGFR pathway are associated with these cancers." (PMID 23874846, 2013). "Mutations in EGFR have been documented in many cancers and impact response to therapy." (PMID 24132149, 2013). "The coexistence of Hh-dependent and-independent Gli activation has been documented by a growing body of evidence in a variety of cancers, and the underlying mechanisms of Hh-independent Gli activation involved multiple signaling pathways, such as TGFβ, EGFR, and RAS and AKT/PI3K pathways." (PMID 23483902, 2013). "Her2 (also known as Neu or ErbB2), a receptor tyrosine kinase belonging to the human epidermal growth factor receptor (EGFR) family that also includes EGFR/Her1, Her3, and Her4, is an important component of cell-signaling networks, and is implicated in the growth of a variety of cancers." (PMID 23878723, 2013). "We aimed to test the hypothesis that cancer-mutated EGFR would cause systems-wide effects by imposing severe modifications to the non-pathological network of molecular interactions." (PMID 24189400, 2013). "Mutations involving EGFR could lead to its constant activation which could result in uncontrolled cell division—a predisposition for cancer." (PMID 26317012, 2013). "Over expression and mutation of EGFR often happen in most cancers." (PMID 23613900, 2013). "Furthermore, the corresponding risk scores derived from the set were found to associate with the efficacy of the anti-cancer drug ZD-6474 targeting EGFR." (PMID 24369726, 2013). "Indeed, 23 patients for whom the tested samples contained less than 25% of cancer cells (<10 and 10–25%) presented an EGFR mutation (23/170; 13.5%)." (PMID 23934203, 2013). "In addition, many cancers are characterized by overexpression and/or mutations that hyperactivate the EGFR." (PMID 23344022, 2012). "Besides the fact that the ErbB receptors are indispensable during development and in normal adult physiology, epidermal growth factor (EGFR) and ErbB2 in particular have been implicated in the development of many human cancers." (PMID 23202898, 2012). "Summary of EGFR mutation status in cell samples of refractory cancer patientsa)." (PMID 22815900, 2012).
cancer (continued). "Cancer cells bearing the B-raf gene mutation have been reported to exhibit resistance to EGFR inhibitors, and ES-2 cells carry this mutation; therefore, we assumed that the ES-2 cells were resistant to the EGFR inhibitors." (PMID 23046546, 2012). "In particular, they demonstrated that 280 nm UV illumination of aromatic residues in proteins causes the disruption of nearby disulphide bridges, where EGFR are excessively populated, leading to the suppression of the proliferative potential in human cancer cell lines." (PMID 22788833, 2012). "MIG-6 down-regulation in non-small cell lung cancer (NSCLC) is associated with increased EGFR signaling and poorly differentiated cancer, while loss of its expression in ErbB2-amplified breast carcinoma renders the cancer cells more resistant to Herceptin, the neutralizing antibody against ErbB2." (PMID 22701735, 2012). "Mutations in the EGFR gene have also been described in a variety of cancers." (PMID 22359620, 2012). "Furthermore DHA induces the upregulation of EGFR tyrosine phosphorylation and the increase of EGFR association with the Sos1 guanine nucleotide protein exchange factor in cancer cell lines including MDA-MB-231." (PMID 22811918, 2012). "Consequently, elevated levels of EGFR have been linked with progressed disease, cancer spread, and poor clinical prognosis." (PMID 22685658, 2012). "Many human cancers are associated with over-expressed epidermal growth factor receptor (EGFR)." (PMID 22554165, 2012). "EGFR was found to harbor mutations in close to 10% of cases, and EGFR inhibitors such as erlotinib could be tested in this subset of cancers." (PMID 21931712, 2011). "EGFR and other ErB receptors may be upregulated or mutated in cancer and this results in changes in downstream signaling partners which can contribute to resistance mechanisms employed by cancer cells." (PMID 21738726, 2011). "EGFR has been implicated in human cancers, where it may contribute to both the initiation and progression of the disease." (PMID 21314332, 2011). "The fusion proteins we developed may provide alternative strategies for therapy of cancers caused by hyper-activation of EGFR signaling." (PMID 21340027, 2011). "Therefore, activation of the EGFR by carvedilol is a greater good due to the role of NO in the cardiovascular system than the hypothetical risk of inducing a cancer." (PMID 21476970, 2011). "Abnormal EGFR signaling is associated with tumorigenic process of various cancers." (PMID 21340027, 2011). "EGFR overexpression and E-cad loss are the major characteristics of aggressive cancers." (PMID 21939503, 2011). "In addition to lung tumor specimens, pleural effusions containing cancer cells can be easily collected and are also available for the detection of EGFR mutations." (PMID 24212826, 2011). "EGFR expression in some types of cancer is also associated with aggressive disease." (PMID 21931642, 2011). "It has been well documented that Wnt and EGFR signaling pathways are closely linked with cancers, but the possible convergence between them is largely unknown." (PMID 20828404, 2010). "Bearing in mind that the TKI gefitinib has recently gained license approval for the treatment of first line NSCLC for patients harboring EGFR mutations, the search for similar biomarkers of response to anti-EGFR agents has become a priority in virtually all cancer types." (PMID 21274259, 2010). "Proteins associated with the human epidermal growth-factor receptor kinase (ERBB or HER) signaling network have proved to be valuable targets for diagnostic imaging with radioimmunoconjugates due to their overexpression in various cancers phenotypes." (PMID 20111600, 2010). "The Epidermal Growth Factor (EGF) receptor (EGFR) is a well-studied member of the ErbB family of receptor tyrosine kinases (RTKs), which are involved in cell fate decisions and are implicated in numerous human cancers." (PMID 20429923, 2010).